SVIL (supervillin)
Description:
[Isoform 1]: Forms a high-affinity link between the actin cytoskeleton and the membrane. Is among the first costameric proteins to assemble during myogenesis and it contributes to myogenic membrane structure and differentiation. Appears to be involved in myosin II assembly. May modulate myosin II regulation through MLCK during cell spreading, an initial step in cell migration. May play a role in invadopodial function. In addition to its cytoskeletal activities, acts as a cofactor or scaffold for KDM1A, facilitating H3K9me2 demethylation and promoting gene activation, especially in neuronal contexts. [Isoform 2]: May be involved in modulation of focal adhesions. Supervillin-mediated down-regulation of focal adhesions involves binding to TRIP6. Plays a role in cytokinesis through KIF14 interaction (By similarity).
Synonyms: MFM10
Tractability: Antibody: its Gene Ontology location is reachable by antibodies, with high confidence; UniProt places it where antibodies can reach, with medium confidence; the Human Protein Atlas places it where antibodies can reach. PROTAC: ubiquitination databases record sites on it; its protein half-life has been measured.
Gene: Protein-coding gene on chromosome 10 (29,457,332 to 29,737,123, reverse strand). Ensembl gene ENSG00000197321.
Subcellular location: Cell membrane; Cytoplasm, cytoskeleton; Cell projection, invadopodium; Cell projection, podosome; Midbody; Cleavage furrow
Subcellular location (Human Protein Atlas): Plasma membrane; Actin filaments; Cytosol
Gene Ontology:
Molecular function: actin filament binding; protein binding; phosphatidylinositol-4,5-bisphosphate binding; actin binding
Biological process: skeletal muscle tissue development; actin filament severing; actin polymerization or depolymerization; barbed-end actin filament capping; positive regulation of cytokinesis; cytoskeleton organization; muscle structure development
Cellular component: actin cytoskeleton; costamere; cytoplasm; focal adhesion; nucleus; plasma membrane; cleavage furrow; microtubule minus-end; midbody; cytoskeleton; podosome
Genetic constraint (gnomAD): Loss-of-function variants: 101 observed, 245.76 expected, observed/expected ratio (o/e) 0.41, 90% interval 0.35 to 0.49. The upper end of that interval is the gene's LOEUF score, 0.49, which puts it in group 2 of 6, group 1 being the genes least tolerant of losing a copy. Missense variants: 2,507 observed, 2,898.2 expected, observed/expected ratio (o/e) 0.87, 90% interval 0.84 to 0.89. Synonymous variants: 994 observed, 1,134.5 expected, observed/expected ratio (o/e) 0.88, 90% interval 0.83 to 0.92.
Homologues: Orthologues: chimpanzee SVIL (99% identical), macaque SVIL (97% identical), dog SVIL (84% identical), pig SVIL (82% identical), guinea pig SVIL (82% identical), mouse Svil (81% identical), rat Svil (80% identical), rabbit SVIL (77% identical), tropical clawed frog svil (58% identical), zebrafish svila (47% identical), Drosophila melanogaster Gel (8% identical), Caenorhabditis elegans gsnl-1 (5% identical), and 1 more. Paralogues in human: FLII (11% identical), VIL1 (11% identical), AVIL (11% identical), VILL (10% identical), GSN (9% identical), SCIN (9% identical), CAPG (4% identical).